HACD2 (3-hydroxyacyl-CoA dehydratase 2)
Description:
Catalyzes the third of the very long-chain fatty acids (VLCFA) elongation four-step cycle (condensation, reduction, dehydration, and reduction). This endoplasmic reticulum-elongation process is characterized by the addition of two carbons to the lipid chain through each cycle. This enzyme catalyzes the dehydration of the 3-hydroxyacyl-CoA intermediate into trans-2,3-enoyl-CoA, within each cycle of elongation. Therefore, it participates in the production of various VLCFAs involved in multiple biological processes as precursors of membrane lipids and lipid mediators.
Synonyms: PTPLB
Tractability: Antibody: UniProt predicts a signal peptide or a membrane-spanning region. PROTAC: ubiquitination databases record sites on it.
Target class: Enzyme; Lyase
Gene: Protein-coding gene on chromosome 3 (123,490,820 to 123,585,081, reverse strand). Ensembl gene ENSG00000206527.
Subcellular location: Endoplasmic reticulum membrane
Pathways (Reactome):
Metabolism: Synthesis of very long-chain fatty acyl-CoAs
Gene Ontology:
Molecular function: 3-hydroxyacyl-CoA dehydratase activity; enzyme binding; protein binding; protein tyrosine phosphatase activity; very-long-chain (3R)-3-hydroxyacyl-CoA dehydratase activity; (2E)-enoyl-CoA hydratase activity
Biological process: fatty acid elongation; sphingolipid biosynthetic process; very long-chain fatty acid biosynthetic process; long-chain fatty-acyl-CoA biosynthetic process; fatty acid biosynthetic process
Cellular component: endoplasmic reticulum; endoplasmic reticulum membrane
Genetic constraint (gnomAD): Loss-of-function variants: 4 observed, 9.73 expected, observed/expected ratio (o/e) 0.41, 90% interval 0.2 to 0.94. That is too few expected variants to judge how well the gene tolerates losing a copy. Missense variants: 158 observed, 143.16 expected, observed/expected ratio (o/e) 1.1, 90% interval 0.97 to 1.26. Synonymous variants: 69 observed, 61.38 expected, observed/expected ratio (o/e) 1.12, 90% interval 0.93 to 1.37.
Homologues: Orthologues: chimpanzee HACD2 (100% identical), macaque HACD2 (99% identical), rabbit HACD2 (97% identical), dog HACD2 (96% identical), pig HACD2 (96% identical), mouse Hacd2 (95% identical), rat Hacd2 (87% identical), tropical clawed frog hacd2 (80% identical), zebrafish hacd2 (78% identical), guinea pig HACD2 (78% identical), Caenorhabditis elegans hpo-8 (41% identical), Drosophila melanogaster Hacd1 (37% identical). Paralogues in human: HACD1 (59% identical), HACD3 (28% identical), HACD4 (24% identical).
Diseases named in the same sentence as HACD2 in open-access papers:
HACD2 is named in the same sentence as 12 diseases in open-access papers, as found by Europe PMC text mining. Sharing a sentence is not in itself a finding about the gene and the disease. The quoted sentences say what the papers report.
Obesity (3 papers, 2022 to 2025). Accumulation of substantial excess body fat. "Our current and previous studies systematically evaluated the dual roles of Hacd2 and revealed that its deficiency protects mice against HFD-induced obesity and MAFLD but impairs metabolic homeostasis under an LFHCD." (PMID 40563962, 2025). "Our previous research indicated that liver-specific Hacd2 ablation (Hacd2LKO) protects mice against high-fat diet (HFD)-induced obesity, hepatic steatosis and diabetes." (PMID 40563962, 2025). "3‐Hydroxyacyl‐CoA dehydratase 2 (HACD2), an obesity‐related gene involved in the elongation of long‐chain fatty acids, is highly expressed in pancreatic cancer (PC) and is associated with patient prognosis." (PMID 39836601, 2025). "Therefore, as an obesity‐related gene, HACD2 could be a potential target for inhibiting PC progression clinically." (PMID 39836601, 2025). "3-hydroxyacyl-CoA dehydratase 2 (Hacd2), a member of the HACD family, has been investigated in obesity and metabolic diseases." (PMID 36312255, 2022). "A recent study in Hacd2LKO mice has revealed ameliorated obesity, hepatic steatosis, and diabetes in HFD-treated mice, which were achieved by upregulating thermogenic genes to enhance energy expenditure, positioning Hacd2 as a therapeutic target." (PMID 40563962, 2025). "Therefore, this study elucidates the mechanism by which the obesity‐related gene HACD2 regulates PC cells proliferation through a noncanonical signaling pathway, which may provide a potential new target and strategy for the individualized clinical treatment of PC." (PMID 39836601, 2025).
amyotrophic lateral sclerosis (1 paper, 2024). Amyotrophic lateral sclerosis (ALS) is a neurodegenerative disease characterized by progressive muscular paralysis reflecting degeneration of motor neurons in the primary motor cortex, corticospinal tracts, brainstem and spinal cord. "A more comprehensive analysis indicates that upregulated proteins (ELOVL5, ELOVL7, TECR, HSD17B4, ACSL1, HACD2, and CBR4) are significantly enriched within the pathways of oxidative phosphorylation and metabolic pathways pertinent to amyotrophic lateral sclerosis." (PMID 39335340, 2024).
diabetes (1 paper, 2025). "Our previous study revealed that Hacd2 deficiency alleviates the fatty liver and diabetes induced by HFD." (PMID 40563962, 2025).
metabolic disease (2 papers, 2022 to 2025). A congenital disorder (due to inherited enzyme abnormality) or acquired (due to failure of a metabolically important organ) disorder resulting from an abnormal metabolic process. "Therefore, targeted interventions involving Hacd2 for metabolic diseases must take into account dietary changes and the functioning of the liver." (PMID 40563962, 2025).
cardiovascular disease (1 paper, 2022). "We noticed that six DEPs (Pltp, Pir, Thbs1, Tmem70, Hacd2, and Ppm1k) closely related to cardiovascular disease were either significantly downregulated or upregulated." (PMID 36312255, 2022).
tumor (1 paper, 2025). "Immunofluorescence staining of tumor tissue from clinical patients also confirmed that the expression levels of HACD2 and PKM2 tended to be consistent." (PMID 39836601, 2025). "Similar results were obtained via western blotting and immunohistochemical analysis of tumor tissues from PANC‐1 tumor‐bearing mice, which revealed that HACD2 knockdown decreased PKM2 expression." (PMID 39836601, 2025). "In addition, lactate levels in the tumor tissues of the HACD2‐knockdown tumor‐bearing mice were decreased, suggesting that HACD2 is indeed involved in the glycolytic process in PC." (PMID 39836601, 2025). "We next investigated whether PRKN could block HACD2‐mediated tumor growth." (PMID 39836601, 2025).
HACD2 also shares sentences with these, for which no sentence is quoted: adenoma (1 paper); colon cancer (1); endometriosis (1); Hepatic steatosis (1); Infertility (1); pancreatic cancer (1).